DSG4 (desmoglein 4)
Description:
A component of desmosome cell-cell junctions which are required for positive regulation of cellular adhesion (By similarity). Coordinates the transition from proliferation to differentiation in hair follicle keratinocytes (By similarity). Plays a role in moderating lymphocyte migration to inflamed skin and maintaining homeostasis of the epidermal inflammatory response (By similarity).
Synonyms: CDHF13; LAH; CDGF13; HYPT6
Tractability: Antibody: UniProt places it where antibodies can reach, with high confidence; its Gene Ontology location is reachable by antibodies, with high confidence; UniProt predicts a signal peptide or a membrane-spanning region. PROTAC: ubiquitination databases record sites on it.
Gene: Protein-coding gene on chromosome 18 (31,376,777 to 31,414,912, forward strand). Ensembl gene ENSG00000175065.
Subcellular location: Cell membrane; Cell junction, desmosome
Pathways (Reactome):
Developmental Biology: Formation of the cornified envelope; Keratinization
Gene Ontology:
Molecular function: protein binding; calcium ion binding
Biological process: cell-cell adhesion; regulation of lymphocyte migration; cell adhesion; homophilic cell-cell adhesion
Cellular component: desmosome; plasma membrane; cornified envelope; membrane
Genetic constraint (gnomAD): Loss-of-function variants: 79 observed, 89.75 expected, observed/expected ratio (o/e) 0.88, 90% interval 0.73 to 1.06. The upper end of that interval is the gene's LOEUF score, 1.06, which puts it in group 4 of 6, group 1 being the genes least tolerant of losing a copy. Missense variants: 1,229 observed, 1,206.8 expected, observed/expected ratio (o/e) 1.02, 90% interval 0.97 to 1.07. Synonymous variants: 376 observed, 422.3 expected, observed/expected ratio (o/e) 0.89, 90% interval 0.82 to 0.97.
Homologues: Orthologues: chimpanzee DSG4 (97% identical), macaque DSG4 (94% identical), dog DSG4 (85% identical), rabbit DSG4 (85% identical), pig DSG4 (84% identical), mouse Dsg4 (82% identical), rat Dsg4 (82% identical), guinea pig DSG4 (80% identical), tropical clawed frog dsg1 (40% identical). Paralogues in human: DSG3 (47% identical), DSG1 (44% identical), DSG2 (37% identical), DSC2 (25% identical), DSC1 (24% identical), DSC3 (24% identical).
Diseases named in the same sentence as DSG4 in open-access papers:
DSG4 is named in the same sentence as 21 diseases in open-access papers, as found by Europe PMC text mining. Sharing a sentence is not in itself a finding about the gene and the disease. The quoted sentences say what the papers report.
hypotrichosis (4 papers, 2020 to 2025). A congenital condition, usually due to genetic aberrations, that is characterized by a lack of hair growth on the head and/or body. "Variants in DSG4 have previously been described in mice and rats with lanceolate hair phenotype, and in human patients with localized autosomal recessive hypotrichosis, as well as monilethrix-like hypotrichosis." (PMID 34878611, 2022).
autosomal recessive hypotrichosis (3 papers, 2022 to 2025). "Additionally, mutations in LPAR6, LIPH, and DSG4 genes have been identified in patients with autosomal recessive hypotrichosis with similar presentations." (PMID 39845463, 2025). "A related phenotype in humans, localized autosomal recessive hypotrichosis (LAH, OMIM #607903), is due to genetic variants in the human ortholog, DSG4." (PMID 34878611, 2022). "In addition, three new genes were identified in patients with autosomal recessive hypotrichosis, including DSG4 mapped to 18q12,1, LIPH to 3q27.3, and P2RY5 to 13q14.11-13q21.33." (PMID 36685177, 2022).
monilethrix (2 papers, 2019 to 2025). Monilethrix is a rare genodermatosis characterized by a hair shaft dysplasia resulting in hypotrichosis. "Among the predicted targets, we identified DSG4, a core protein essential for normal hair follicle differentiation, which is linked to Monilethrix, a hair loss disorder caused by the mutations in DSG4." (PMID 40389837, 2025). "Most of the cases of monilethrix are caused by variants in keratin genes, but it is also described with variants in the desmoglein 4 gene (DSG4)." (PMID 30794648, 2019).
psoriasis (2 papers, 2020 to 2021). An autoimmune condition characterized by red, well-delineated plaques with silvery scales that are usually on the extensor surfaces and scalp. "The present results support the notion that Dsg-4 deficiency promotes inflammation and alters epidermal integrity during inflammation in an experimental psoriasis-like model." (PMID 33995349, 2021). "The clinical importance of our data resides mainly on the potential use of Dsg-4 as a biomarker for screening, diagnostic, prognostic, and monitoring immune-mediated skin diseases such as psoriasis and several dermatitis-like illnesses." (PMID 33995349, 2021). "Our approach using IMQ-induced inflammatory skin disease on rats does not replicate all features of psoriasis but is nevertheless a pertinent tool to explore the immunological and cutaneous events underlying desmoglein 4 deficiency in rats." (PMID 33995349, 2021). "However, their role in inflammation has been barely studied, and whether desmoglein-4 modulates psoriasis lesions is completely unknown." (PMID 33995349, 2021). "The focus of this work was to evaluate the role of Dsg-4 in modulating skin inflammation following administration of topical imiquimod (IMQ), a Toll Like Receptor 7 (TLR7) ligand, which is experimentally used to emulate a psoriasis-like dermatitis." (PMID 33995349, 2021).
COVID-19 (1 paper, 2023). A disease caused by infection with severe acute respiratory syndrome coronavirus 2. "Among these, four (CLEC4A, DSG4, FAM3B, and RARRES1) displayed significantly lower levels in both moderate and severe COVID-19, as compared to the healthy controls and the sepsis cohorts." (PMID 36829233, 2023).
dermatitis (1 paper, 2021). An inflammatory process affecting the skin. "In this study, we assessed the impact of desmoglein-4 deficiency on the severity of imiquimod (IMQ)-induced skin inflammation and psoriasiform lesions." (PMID 33995349, 2021). "To evaluate the role of Dsg-4 in the skin immune response, we induced acute skin inflammation in OFA and wild-type SD rats by topical administration of IMQ." (PMID 33995349, 2021). "Therefore, determining whether Dsg-4 is relevant in skin inflammation will provide further insight into the pathogenesis of PSO and immune mediated skin diseases as well." (PMID 33995349, 2021). "Similarly, OFA rats also showed no signs of spleen disorder despite exacerbated skin inflammation in response to IMQ suggesting that inflammatory events related to Dsg-4 deficiency may not reach distant tissues." (PMID 33995349, 2021).
Hyperkeratosis (1 paper, 2021). Hyperkeratosis is a histopathological term defining a thickened stratum corneum and may be present in many different skin conditions, with many possible overlaps. "We show that Dsg-4-deficient rats developed a more severe inflammatory phenotype with sharp hyperkeratosis following topical IMQ administration than Sprague–Dawley (SD) rats." (PMID 33995349, 2021). "The lack of Dsg-4 interferes with the epithelial response to IMQ as evidenced by severe hyperkeratosis and parakeratosis, intense hydropic degeneration of basal cells, and marked vascular proliferation." (PMID 33995349, 2021).
hypohidrosis (1 paper, 2024). diminished sweating in response to appropriate stimuli. "Interestingly, ED9 exhibited hypohidrosis, whereas typically DSG4-mutation positive patients show normal sweating." (PMID 39244550, 2024).
hypotrichosis simplex (1 paper, 2022). Hypotrichosis simplex (HS) or hereditary hypotrichosis simplex (HHS) is characterized by reduced pilosity over the scalp and body (with sparse, thin, and short hair) in the absence of other anomalies. "Several genes have been identified as being associated with hypotrichosis simplex, including LPAR6, LIPH, and DSG4." (PMID 36685177, 2022).
inflammatory skin disease (1 paper, 2021). Inflammatory skin disorders covers a broad category that includes many conditions ranging in severity, from mild itching to grave medical health complications These disorders are common in people of all ages and races. "To determine whether a decreased Dsg-4 level is associated with inflammatory skin diseases, we evaluated differential expressed genes (DEG) in PSO, AD, and healthy controls using available datasets." (PMID 33995349, 2021). "When we compared PSO vs. AD to evaluate desmosome profiling similarities in inflammatory skin diseases, we found that DSG4, DSP, DSG2, and PKP2 displayed less than a two-fold difference in gene expression." (PMID 33995349, 2021).
Psoriasiform dermatitis (1 paper, 2021). A skin abnormality characterized by redness and irritation, with thick, red skin that displays flaky, silver-white patches (scales). "An association between Dsg-4 deficiency and exacerbated psoriasiform dermatitis was demonstrated by an intense leukocyte infiltration in OFA rats in response to IMQ." (PMID 33995349, 2021).
systemic sclerosis (1 paper, 2022). A chronic disorder, possibly autoimmune, marked by excessive production of collagen which results in hardening and thickening of body tissues. "Morphea patients also exhibited increased Cytokeratin 14 and DSG4 antibodies compared to healthy controls and systemic sclerosis cases by NFI." (PMID 35073943, 2022).
infection (1 paper, 2021). The state of being infected such as from the introduction of a foreign agent such as serum, vaccine, antigenic substance or organism. "Due to the possibility that Dsg4 deficiency causes an unspecific barrier breakdown that may facilitate infection and secondary inflammation, we evaluate the microbiological status of the IMQ-treated and untreated skin zones." (PMID 33995349, 2021).
DSG4 also shares sentences with these, for which no sentence is quoted: tumor (2 papers); eczema (1); ichthyosis (1); lipodystrophy (1); peeling skin syndrome (1); retinitis pigmentosa (1); Sepsis (1); spleen disorder (1).